RNY3P3 (RNY3 pseudogene 3)
Gene: Miscellaneous RNA gene on chromosome 13 (78,355,227 to 78,355,328, reverse strand). Ensembl gene ENSG00000200686.
Homologues: Orthologues: macaque Y_RNA (93% identical). Paralogues in human: RNY3 (86% identical), Y_RNA (86% identical), Y_RNA (85% identical), RNY3P1 (84% identical), Y_RNA (84% identical), Y_RNA (83% identical), RNY3P11 (82% identical), RNY3P16 (82% identical), RNY3P9 (82% identical), Y_RNA (82% identical), Y_RNA (81% identical), RNY3P14 (80% identical), and 92 more.